CCL2 (C-C motif chemokine ligand 2)
Diseases named in the same sentence as CCL2 in open-access papers (continued):
Sharing a sentence is not in itself a finding about the gene and the disease.
myopia (11 papers, 2018 to 2025). "In age- and sex-adjusted allele-based tests, three loci were associated with high myopia: CCL2 rs2857656, TGFβ1 rs2317130, and MMP1 rs2071230 (P = 0.04, 0.03, and 0.04, respectively)." (PMID 41138034, 2025). "In this study, we confirmed the reduced function of the BOB/BBB after the induction of high myopia, which was reversed by Ccl2 deficiency, suggesting a role for CCL2 in the high myopia-related disruption of BOB/BBB." (PMID 37699875, 2023). "CCL2 SNPs (rs2857656, rs3760396) were significantly associated with high myopia in our cohort." (PMID 41138034, 2025). "In conclusion, our study provides evidence linking inflammation-related gene polymorphisms—particularly in CCL2, TGFβ1, MMP1, and IL1β—to high myopia in children." (PMID 41138034, 2025). "The levels of IL-6 and CCL2 in the tears from patients with high myopia were significantly increased, and correlated with the severity of myopic maculopathy." (PMID 40909333, 2025). "At rs3760396 (CCL2), genotype distributions differed between high myopia and control group (P = 0.04): in cases, G/G 77.2%, G/C 21.4%, C/C 1.3%; in controls, G/G 86.1%, G/C 11.1%, C/C 2.8%." (PMID 41138034, 2025). "In the macular holes with high myopia, the levels of the inflammatory cytokines C-C motif chemokine ligand 2 (CCL2), C-X-C motif chemokine ligand 10 (CXCL10), and interferon-gamma (IFNG) in the vitreous are significantly elevated." (PMID 40657400, 2025). "CCL2 expression and monocyte infiltration in the eye were reduced by recovery of high myopia, suggesting that elevated CCL2 may be a key mediator between myopic visual stimulation and the subsequent myopia-induced inflammation." (PMID 37699875, 2023). "After recovery from high myopia, upregulated CCL2 in highly myopic eyes was reversed in mice." (PMID 37699875, 2023). "The C-C motif chemokine ligand-2 (CCL2) can recruit monocytes to differentiate into macrophages, and the infiltrating macrophages express high levels of MMP-2, which promotes myopia progression." (PMID 40909333, 2025).
sarcoma (11 papers, 2007 to 2025). A usually aggressive malignant neoplasm of the soft tissue or bone. "Interestingly, all of these genes, with the exception of Foxc2, have been previously associated with various types of sarcoma in either human or rodent studies and increased CCL2 gene expression has been directly correlated with histiocytic sarcoma in canine patients." (PMID 27105514, 2016). "Finally, to investigate whether M2-like macrophages are associated with CCL2 expression in sarcoma patients, we evaluated the infiltration of 22 immune cell subsets in sarcoma tissues using CIBERSORT analysis of 868 clinical samples obtained from 5 publicly available RNA-Seq datasets." (PMID 40343498, 2025). "CCL2 has been shown to have direct effects on tumor growth in an autocrine and paracrine fashion in multiple cancers, including breast, lung, cervix, ovary, sarcoma, and prostate." (PMID 32471499, 2020). "Furthermore, we determined in a syngeneic sarcoma mouse model that radiation up-regulates IRF3, IFNβ, and the T cell chemokines CCL2 and CCL5 in the tumor microenvironment, which are associated with activation and increased infiltration of Th1/Tc1 T cells in the tumor microenvironment." (PMID 27014915, 2016).
unstable angina (11 papers, 2009 to 2025). "On the other hand, concentrations and mRNA expression levels of CCL2, CCL5, and CX3CL1 have also been evaluated in patients with acute myocardial infarction and unstable angina, patients with stable angina, and patients without coronary heart disease." (PMID 40508161, 2025).
Ureteral obstruction (11 papers, 2011 to 2025). Obstruction of the flow of urine through the ureter. "The study qualifies CCL2/MCP-1 mRNA expression as a prognostic marker of partial ureteral obstruction." (PMID 24692841, 2014). "Crisman and coworkers detected the expression of CCL2/MCP-1, CCL5/RANTES, and CXCL10/IP-10 at 1 day of unilateral ureteral obstruction in mice." (PMID 24692841, 2014).
adenoma (10 papers, 2014 to 2025). A neoplasm arising from the epithelium. "All associations were inverse; that is, CCL2 expression in colorectal adenomas decreased along with the increasing number of polyps, and the patient’s age and was lower in adenomas with high grades of dysplasia and dominant villous components." (PMID 34884259, 2021). "Of those variables, CCL2 expression was independently associated with the grade of dysplasia, growth pattern, number of adenomas, and patient’s age, which together explained 22% of the variability in gene expression." (PMID 34884259, 2021). "The strongest association was noted for adenoma expression of CCL2." (PMID 34884259, 2021). "Pairwise analysis confirmed this trend with 64% of paired samples exhibiting a higher CCL2 expression in adenomas (p = 0.009)." (PMID 40699620, 2025). "CCL2 expression was significantly higher in adenomas (mean: 4.23) than in adenocarcinomas (mean: 3.97, p = 0.002)." (PMID 40699620, 2025). "CCL2 is downregulated in adenoma but significantly upregulated in metastasis samples, which aligns with previous findings that it promotes liver metastasis." (PMID 39409185, 2024). "Here, we showed that CCL2 expression in polyps and the polyp-to-normal expression ratio were lower in patients with large and multiple polyps and adenomas with a dominant villous growth pattern and high-grade dysplasia." (PMID 34884259, 2021). "CCL2 expression in the adenomas with high-grade dysplasia was significantly decreased compared with the adenomas with low-grade dysplasia (by 2.8-fold)." (PMID 34884259, 2021). "A stepwise method was applied to co-analyze the effect of the dysplasia grade, adenoma growth pattern, adenoma size, number of polyps, and subsite and patient’s age and sex on CCL2, CCL7, and CCL7 expression in colorectal adenomas." (PMID 34884259, 2021). "Their expression in the polyp and expression rate mimicked the CCL2 patterns; they were lower in the larger polyps and adenomas with a higher grade of dysplasia and decreased with the increasing contribution of the villous growth pattern." (PMID 34884259, 2021). "Both the fold change in expression of CCL2, CCL7, and CCL8 and gene expression in adenoma were inversely correlated with a cumulative risk of transformation." (PMID 34884259, 2021). "CCL2, CCL7 and CCL8 expression tended to decrease in the polyps compared with the normal tissue, though more markedly in the case of adenomas with high-grade dysplasia." (PMID 34884259, 2021). "CCL2, CCL7, and CCL8 expression was the highest in the hyperplastic polyps and lower in the adenomas, in which it gradually decreased along with an increasing villous component." (PMID 34884259, 2021). "The fold change in CCL2, CCL7, and CCL8 expression decreased gradually along with an increasing villous component in the adenomas." (PMID 34884259, 2021). "Finally, we found that SASP transcripts were elevated in about 59–61% of adenomas, both using two SASP signatures and a single-gene level that included genes such as CCL2, CXCL2, FOXO4, and NKFB1 and 2, highlighting the proinflammatory milieu often accompanying OIS." (PMID 40699620, 2025).
alcohol (10 papers, 2012 to 2023). "Other clinical studies have indicated that alcohol dependence is characterized by enhanced glial IL-1β in the cerebral cortex and elevated chemokine monocyte chemotactic protein 1/MCP-1 (CCL2) in different brain regions." (PMID 30870525, 2019). "In addition, Stat3 in hepatocytes is involved in induction of CXCL2 and CCL2 expression followed by increased infiltration of inflammatory cells in an alcohol liver injury model." (PMID 31718093, 2019).
alveolitis (10 papers, 2006 to 2024). "While we did not observe significant interstitial fibrosis in T-bet-/- mice treated with NiNPs, we did observe chronic alveolitis and found that anti-CCL2 treatment only caused a slight decrease in alveolitis." (PMID 24499286, 2014). "In general, CCL2 has opposing effects in regulating mucous cell metaplasia and alveolitis or fibrosis in response to a variety of environmental agents including NiNPs." (PMID 24499286, 2014). "The role of CCL2 in mediating NiNP-induced mucous cell metaplasia and alveolitis was analyzed by blocking CCL2 activity using a monoclonal antibody." (PMID 24499286, 2014). "We also found that CCL2 is enhanced in T-bet-/- mice and blocking CCL2 activity with a neutralizing antibody increased NiNP-induced mucous cell metaplasia in these mice, while marginally reducing NiNP-induced alveolitis." (PMID 24499286, 2014). "High CCL2 and IL-8 BALF concentrations were associated with neutrophilic and mixed alveolitis." (PMID 19615053, 2009). "Therefore we hypothesized that CCL2 could be responsible for increased mucous cell metaplasia and parenchymal alveolitis seen in T-bet-/- mice exposed to NiNPs." (PMID 24499286, 2014). "Observations revealed a decisive role of the CCL2/CCR2 axis in driving M1 macrophage polarization, and this type of macrophages was confirmed to boost alveolitis in leading myofibroblast activation." (PMID 38273656, 2024). "In combination with data from scRNA-seq of patients and a murine IPF model, a decisive role of CCL2/CCR2 axis in driving M1 macrophage polarization was revealed, and M1 macrophage was further confirmed to boost alveolitis in leading myofibroblast activation." (PMID 38273656, 2024). "Treatment of T-bet-/- mice with a monoclonal anti-CCL2 antibody enhanced NiNP-induced mucous cell metaplasia and MUC5AC mRNA levels (p < 0.05), yet marginally reduced NiNP-induced alveolitis." (PMID 24499286, 2014). "Nasal inoculation of cotton rats with a recently isolated EV-D68 strain (VANBT/1) significantly upregulated pulmonary cytokine mRNA levels (CCL2, CCL5, CXCL1, CXCL10, IL-6, IFN-β, and IFN-γ) and provided histological evidence of peribronchiolitis and alveolitis." (PMID 34887856, 2021). "The levels of CCL2 were elevated in every stage of pulmonary sarcoidosis, in those with or without alveolitis and in those on or off immunosuppressive therapy." (PMID 21463523, 2011). "Using immunohistochemical techniques we determined the cellular sources of CCL2 during all stages of pulmonary sarcoidosis including those with and without alveolitis and those on or off empiric therapy." (PMID 21463523, 2011). "Our results suggest that expression of CD206, CD163, CCL2 and TGFβ is high in IPF patients as compared to a chronic inflammatory condition that does not progress to fibrosis, hypersensitivity pneumonitis." (PMID 28817691, 2017).
bacterial pneumonia (10 papers, 2012 to 2025). Acute infection of the lung parenchyma caused by bacteria (e.g., Streptococcus pneumoniae, Haemophilus influenzae, Chlamydia pneumoniae, Mycoplasma pneumoniae, and Legionella pneumophila). "Taken together with the result that the monocyte chemoattractant protein-1 (MCP-1)/CCL2 improved efferocytosis in murine bacterial pneumonia to resolve acute lung inflammation, chemokines that attract inflammation cells have a dual function." (PMID 32346605, 2020). "CCL2 treatment, improved efferocytosis, and subsequent resolution in bacterial pneumonia and increased survival from bleomycin-induced lung injury." (PMID 33664739, 2020). "In the context of bacterial pneumonia, Ccl2 knockout mice have been shown to exhibit a decreased monocytic immune response." (PMID 27282780, 2016). "Notably, CCL-2 and MIP-1α are elevated in the lungs of bacterial pneumonia patients, and our own studies showed that NS1619 reduced the levels of these two cytokines in both mice and human lung endothelial cells." (PMID 40830381, 2025).
bipolar disorder (10 papers, 2016 to 2023). A disorder of the brain that causes unusual shifts in mood, energy, activity levels and the ability to carry out day-to-day tasks. "Considering a similar correlative elevation of CCL2 levels reported in patients diagnosed with bipolar disorder, more research is needed in order to effectively use elevated serum CCL2 levels as a marker of MDD." (PMID 31075818, 2019).
bone cancer (10 papers, 2009 to 2024). A primary or metastatic malignant neoplasm affecting the bone or articular cartilage. "It has been suggested that the PD‐L1/PD‐1 signaling pathway can exert analgesic effects on bone cancer pain in mice by inhibiting TRPV1 activity in primary sensory neurons via SHP‐1 to delay pain or by suppressing PD‐L1/CCl2‐mediated osteoclastogenesis and protecting against bone destruction." (PMID 38961264, 2024). "In the bone cancer pain model, the upregulation of PD-L1 promotes the secretion of CCL2, which selectively activates C-fiber nociceptive neurons in DRG and drives the pathogenesis of bone cancer pain." (PMID 38643205, 2024).
cataract (10 papers, 2009 to 2026). Partial or complete opacity of the crystalline lens of one or both eyes that decreases visual acuity and eventually results in blindness. "CCL2, DUSP1, FAS and transcription factor c-Jun may be used as specific therapeutic molecular targets in order to treat cataracts induced by GCs." (PMID 25672806, 2015). "On the other hand, genes which are highly up-regulated in Dbl-lenses, such as Mmp12, Ccl2, and Spp1, have not been described in EMT occurring in these cataracts." (PMID 19759912, 2009).
intracerebral hemorrhage (10 papers, 2018 to 2025). A cerebrovascular disorder characterized by bleeding into one or both cerebral hemispheres including the basal ganglia and the cerebral cortex. "Recent evidence has shown that MCP-1/CCL2 is involved in disruption of the blood-brain barrier in the context of cerebral damage, such as intracerebral hemorrhage." (PMID 35479062, 2022). "TBI and intracerebral hemorrhage patients show elevated plasma and serum levels of CCl2 as early as 2 h onwards and show poor outcomes." (PMID 32684835, 2020). "Interestingly, treating with TGFβ-1 did not increase CCL2 gene expression and led to improved function in a microglia-mediated inflammation study of intracerebral hemorrhage." (PMID 31829243, 2019).
leptospirosis (10 papers, 2018 to 2024). A contagious bacterial infection caused by spirochetes of the genus Leptospira. "Aligned with our findings, narrative reviews discussed the renal dysfunction associated with leptospirosis that resulted in secretion/expression of Fibronectin, iNOS, CCL2/MCP-1, TNFα, NFκB, CCL2/MIP2, CXCL1/KC through TLR2." (PMID 39729468, 2024). "The correlation analysis of detected chemokines CXCL11, CXCL9, CCL3, and CCL2 helps to clarify the role of each cytokine in leptospirosis." (PMID 39534703, 2024). "Notably, we observed the secretion/mRNA expression of several cytokines (IL6, IL8, IL-1β, TNFα, IFNγ, IL10, CCL2/MCP-1, CCL10, COX2, CXCL1/KC, CXCL2/MIP2) and immune effectors (hBD2, iNOS, Fibronectin, Oxygen, and Nitrogen reactive species) as key aspects of host TLR2 responses during leptospirosis." (PMID 39729468, 2024). "In previous studies, we have shown that CCL2, CXCL5, and CCL8 are involved in the leptospirosis process, although the mechanisms are not understood." (PMID 39534703, 2024).
liver failure (10 papers, 2012 to 2025). A liver disease characterized by the liver losing or has lost all of its function. "Of note, CCL2 serum concentrations in a pediatric study cohort correlated with clinical disease severity, transaminase levels, and coagulopathy and highest CCL2 levels were associated with fatal outcome in patients with acetaminophen-induced liver failure." (PMID 23091461, 2012). "Further examinations confirmed that CCL2 was significantly elevated in rats with liver failure." (PMID 39478979, 2024). "One possible explanation to an inverse relationship between the levels of CCL-2 and the severity of chronic liver disease is that the metabolic activity of CCL-2 responsive neutrophils and other infiltrating white blood cells diminishes together with the intensification of liver failure." (PMID 23405244, 2013). "Taken together with previous studies, these findings support the hypothesis that following liver failure, bile acids are elevated in the circulation, gain entry into the brain and bind S1PR2 on neurons, which secrete CCL2 and lead to the activation of microglia." (PMID 28725183, 2017).
Peritoneal Fibrosis (10 papers, 2012 to 2025). Disorder characterized by a wide range of structural changes in PERITONEUM, resulting from fibrogenic or inflammatory processes. "Besides, CCL2 participatesin the initiation and progression of peritoneal fibrosis, which can modify thebiology of resident cells, stimulating epithelial-mesenchymal transition of theperitoneal membrane, and once again promoting the loss of its functionality." (PMID 34032817, 2021).
prostatitis (10 papers, 2015 to 2025). An infectious or non-infectious inflammatory process affecting the prostate gland. "Our results reveal that PARP1 aggravated prostatitis, and promoted macrophage and neutrophil infiltration at inflammatory sites and upregulates the expression of inflammatory cytokines such as IL-6, CCL2, and TNF." (PMID 40032778, 2025). "In the study of pain, we used IF experiments to measure the expression of the prostatitis pain-related factor CCL2, and its expression was significantly decreased after treatment (p < 0.001)." (PMID 36263126, 2022). "Together, both in vivo mouse assay and in vitro cell migration assay conclude that ASC-J9® can reduce the prostatitis via reduction of the CD4+ T cell migration to the prostate that involved the modulation of the CCL2 expression." (PMID 27564257, 2016). "Importantly, early studies also indicated that CCL2 is an essential mediator for the development of prostatitis." (PMID 27564257, 2016). "Therefore, we believe ASC-J9® effect may function through a AR-independent pathway to modulate CCL2 in prostatitis." (PMID 27564257, 2016). "Because the roles of the CCL2/CCR2 axis in spinal macrophage recruitment have been elucidated, we focus on the roles of CXCL10 in neuroinflammation and pain in chronic prostatitis." (PMID 39718951, 2025). "C57BL/6 mice received 5 mg/kg body weight of 1-adrenergic or 2-adrenergic receptor agonists intraperitoneally for five days and developed chronic prostatitis, characterized by increased pro-inflammatory cytokines TNF, IL-6, and chemokines CCL2, CCL3." (PMID 37228599, 2023). "Mechanistically, PARP1 promote the NF-κB expression, which could regulate downstream inflammatory cytokines, including IL-6, IL-10, IL-12p70, CCL2, IFN-γ in M1 macrophages, leading to the accumulation of proinflammation factors and ultimately exacerbating prostatitis." (PMID 40032778, 2025). "Moreover, recent studies have identified CCL2 and CCL3 as significant biomarkers for inflammatory IIIA and non-inflammatory IIIB chronic pelvic pain symptoms, underscoring their potential clinical significance in the diagnosis and management of prostatitis." (PMID 37228599, 2023). "Additionally, the expression of IL-6, IL-12p70, CCL2 and TNF in the Parp1−/− model group was markedly reduced and IL-10 increased significantly compared to that in the WT model group, suggesting that PARP1 enhanced the inflammatory factors secretion in prostatitis." (PMID 40032778, 2025). "CCL2 and CCL3 expression levels have been found to be altered in prostatitis, although they are not necessarily markers." (PMID 37228599, 2023).
psoriatic arthritis (10 papers, 2018 to 2024). Joint inflammation associated with psoriasis. "Using a panel of eight biomarkers (PIIANP, TIMP-1, ADAMTS-4, CCL2, IP-10 and TGF-β3), this model distinguishes between OA, knee injury and inflammatory knee arthritis (i.e. RA or psoriatic arthritis) with almost 100% efficacy." (PMID 34804052, 2021).